TNF (tumor necrosis factor)
Diseases named in the same sentence as TNF in open-access papers (continued):
Sharing a sentence is not in itself a finding about the gene and the disease.
joint disease (continued). "Although NO has been described as a meniscal product in several joint diseases and as an important mediator of meniscal tissue degradation in several studies, we did not see a stimulating influence of NO on the TNFα-induced GAG release or aggrecan cleavage." (PMID 19778432, 2009). "Undiagnosed, subclinical arthropathy could explain elevated TNF-α levels despite no reported joint pain." (PMID 40869598, 2025). "Under the influence of joint disease, many cytokines and collagen turnover biomarkers accumulate in synovial fluid, including COMP, CC-chemokine ligand 5 (CCL5), matrix metalloproteinase-1 (MMP-1), MMP-3 and MMP-18, as well as tumor necrosis factor-alpha (TNF-α), interleukin-6 (IL-6) and IL-8." (PMID 36835530, 2023). "Although often considered a “non-inflammatory” joint disease, it is increasingly being recognized that cytokines, particularly IL-1β, and tumor necrosis factor-α (TNFα) may play an important role in both the progressive degradation of the cartilage and the disease symptoms." (PMID 23889808, 2013). "This concept is further supported by the observation that mice lacking iRhom2 are protected from bone resorption in a mouse model of hemophilia arthropathy, as are mice lacking the ADAM17 substrate TNFα or mice treated with the TNF antagonist Etanercept." (PMID 33227998, 2020). "Importantly, the present results regarding BTM should not be extrapolated to any possible effect of TNF-α blocking therapy on radiographic progression in AS since no imaging method was used to measure new bone formation resulting in the formation of syndesmophytes and joint ankylosis." (PMID 22546520, 2012). "Finally, the bone and joint disease correction and lack of secondary storage-mediated amplification following TLR4 knock-out in MPS VII mice further proves the pivotal role of TNF-α in the periphery, as opposed to IL-1β." (PMID 35216110, 2022).
pulmonary edema (68 papers, 2010 to 2026). Accumulation of fluid in the lung tissues causing disturbance of the gas exchange that may lead to respiratory failure. "Proinflammatory cytokines such as IL-6, TNF-α, and IL-1β were found to be associated with brainstem encephalitis complicated by pulmonary edema in EV-A71 infections." (PMID 40377310, 2025). "In vivo and in vitro experiments have demonstrated that TNF-α increases alveolar capillary wall permeability under pathological conditions, causing pulmonary edema." (PMID 39650159, 2024). "Both of these activities of TNF are implicated in the pathogenesis of pulmonary edema, which is often associated with ALI." (PMID 29354115, 2017). "In addition, the increase of the ratio of W/D weight as a key indicator of the severity of pulmonary edema and the pro-inflammatory factor levels of IL-1β, IL-6, and TNF-α caused by PQ was reverted back by Andro." (PMID 37275765, 2023). "Digoxin significantly reduced pulmonary edema in the therapeutic group (p = 0.02) and decreased TNF-α levels (p = 0.014), while robustly suppressing IL-6 and MDA in both prophylactic and therapeutic settings (each p < 0.001)." (PMID 41693482, 2026). "TNF, the most widely studied pleiotropic cytokine, seems to have a dual role, which means it does not only promote the regression of pulmonary edema, it also helps to stimulate lung fluid clearance." (PMID 35725416, 2022). "The pro-inflammatory cytokine, such as tumor necrosis factor (TNF), has been shown to contribute to the development of pulmonary edema and alveolar fluid reabsorption." (PMID 35725416, 2022). "IL-10, IL-13, IL-1β, IL-6, tumor necrosis factor-α (TNF-α), and interferon-γ (IFN-γ) also have been shown in previous studies to predict the occurrence of EV71-associated pulmonary edema." (PMID 36366337, 2022). "TNF has been reported to be involved in early inflammatory response and stretch-induced pulmonary edema." (PMID 33927789, 2021). "Pulmonary edema, impaired of fluid clearance, neutrophilic infiltration, and elevated concentrations of TNF-α in BALF." (PMID 34887773, 2021). "HFMD patients with brainstem encephalitis or pulmonary edema, or a combination of the two conditions, display diverse plasma levels of IL-8 and TNF-α, with IL-8, IP-10, and IL-4 cytokine levels identified as disease progression predictors." (PMID 34069574, 2021). "Proinflammatory cytokine tumor necrosis factor (TNF) plays a dichotomous role in the reabsorption of pulmonary edema." (PMID 33673381, 2021). "In these studies, SEV significantly improved the oxygenation of lung grafts and reduced pulmonary edema through the reduction of IL-1β, IL-6, and TNF-α." (PMID 33506025, 2021). "In more than 20-year-old studies, which examined the pulmonary effects of human TNF in vivo, increased microvascular permeability with subsequent pulmonary edema and acute lung injury were reported." (PMID 32410851, 2020). "Beta-sitosterol can significantly reduce LPS-induced pulmonary edema and inflammatory response and reduce the release of TNF-a and IL-6." (PMID 33335558, 2020). "The TNF-R1 promotes death signaling, pulmonary neutrophil sequestration, and edema formation, whereas the TNF-R2 was shown to protect against pulmonary edema and to attenuate TNF-mediated inflammatory responses." (PMID 32410851, 2020). "Reduced lung inflammation and pulmonary edema.A decrease in IL-1, IL-1 β, IL-6, and TNF-α levels.Restoration of Treg/Th17 balance." (PMID 32519302, 2020). "Inhibits neuraminidase activity, reduces lung index, alleviates pulmonary edema, reduces inflammatory factors TNF-α, IL-1β, increases PI3K protein expression, and reduces the protein expression of p-Akt, caspase-3 and NF-κB." (PMID 33192523, 2020). "Improved oxygen saturation.Reduced lung inflammation and pulmonary edema.Reduced IL-6 and TNF-α levels." (PMID 32519302, 2020).
pulmonary edema (continued). "Together with its previously discussed effects on ENaC, these data suggest a role for the TNF tip peptide as a potential therapeutic agent in pulmonary edema, since the two main mediators of Na+ transport are both activated by the TNF tip peptide." (PMID 29354115, 2017). "In conclusion, an intravenous continuous administration of adrenaline after hepatic inflow obstruction significantly deteriorated pulmonary edema, impaired oxygenation, and increased the alveolar TNF-α concentration during high-tidal volume ventilation." (PMID 26807260, 2016). "Several cytokines and chemokines, including tumor necrosis factor α (TNF-α), IL-1β,-6, −10,-8 and-13 and IFN-γ, were indicated to be associated with brainstem encephalitis (BE) and pulmonary edema (PE) caused by EV71 infection in the previous studies." (PMID 26058678, 2015). "Inhalation of TIP peptides that mimic the lectin-like domain of TNF-α is a novel approach to attenuate pulmonary oedema on the threshold to clinical application." (PMID 24904234, 2014). "The lectin-like domain of TNF-α mimicked by an inhaled TIP peptide represents a novel approach to attenuate a pulmonary edema in respiratory failure, which is on the threshold to clinical application." (PMID 24070340, 2013). "The perfusion with TNF-α Ab also prevented CPB-induced pulmonary edema and improved oxygenation index." (PMID 24386164, 2013). "The TIP peptide, a synthetic mimic of the lectinlike domain of TNF, can significantly increase alveolar fluid clearance and improve lung compliance in pulmonary edema models." (PMID 21188088, 2010). "The proinflammatory cytokine tumor necrosis factor (TNF) has been shown to contribute to the pathogenesis and development of pulmonary edema." (PMID 21188088, 2010). "Elevated circulating levels of pro-inflammatory cytokines, including IL-1β, IL-6, IL-8, and tumor necrosis factor-α (TNFα), have been consistently observed in both preclinical models and patients with PH, as well as in individuals with high-altitude pulmonary edema." (PMID 41596221, 2026). "In vivo study revealed that DHK attenuated wet/dry weight ratio of lung tissue, lung neutrophil intrusions and pulmonary oedema, and reduced the increased total cells, neutrophils, TNFα and IL1β expression in bronchoalveolar lavage fluid (BALF) in LPS‐stimulated BALB/c mice." (PMID 40857065, 2025). "Similarly, TNF-α, another pro-inflammatory cytokine, contributes to systemic inflammation by increasing vascular permeability and exacerbating pulmonary edema and hypoxia." (PMID 40137715, 2025). "A large number of cytokines, such as TNF-α and IL-6 release, lead to neutrophil aggregation in lung tissue, destruction of alveolar epithelial structure, ECM damage, and alveolar-capillary membrane injury, thereby causing exudative pulmonary edema." (PMID 32765635, 2020). "As a cytokine with a primary and strong effect, TNF-α can damage vascular endothelial cells, inhibit the release of the alveolar surface-active substances, and increase alveolar capillary permeability and pulmonary edema." (PMID 29619068, 2018). "Administration of QYT may reduce the extent of pulmonary edema by decreasing the expression levels of TNF-α; therefore, protecting pulmonary function." (PMID 25371738, 2014). "In our study, we firstly showed that EGCG pretreatment significantly improved hypoxemia and histopathologic changes, alleviated pulmonary edema and lung vascular leak, reduced the level of TNF-α and IL-1, and increased the production of IL-10 in seawater aspiration-induced ALI rats." (PMID 24692852, 2014). "In this review, we will discuss the dual role of TNF in pulmonary edema." (PMID 21188088, 2010). "By inhibiting NF-κB–dependent transcription of pro-inflammatory cytokines (TNF-α, IL-1β, IL-6) and attenuating oxidative stress, deslanoside may help preserve alveolar–capillary barrier integrity, reduce endothelial permeability, and alleviate pulmonary edema." (PMID 41244837, 2025).
pulmonary edema (continued). "Previously published data have demonstrated in cases of high-altitude pulmonary edema, there is an increase in the infiltration of inflammatory cells, specifically macrophages and neutrophils, as well as elevated levels of cytokines such as IL-6, TNF-α, and IL-1β." (PMID 38166725, 2024). "One study indicated that patients with brainstem encephalitis and pulmonary edema exhibit elevated serum and CSF levels of IL-6, TNF-α, IL-1β, and IFN-γ, suggesting that pulmonary edema may result from increased vascular permeability due to systemic inflammation." (PMID 39767680, 2024). "TNF-α and IL-6 are important cytokines in the development of ALI, which can activate the endothelial cells and lead to pulmonary edema." (PMID 35281058, 2022). "Tumor-necrosis factor (TNF)-α-derived TIP peptide: As with vasculotide, the major potential clinical application of TNF-derived TIP circular peptide, which is based on the lectin-like domain of TNF-α, is in reducing pulmonary edema in patients with ALI/ARDS." (PMID 29641429, 2018). "Many agonists, including tumor necrosis factor (TNF)-α and platelet activating factor (PAF) stimulate ceramide production and PAF-induced pulmonary edema is partly mediated by ASM and ceramide." (PMID 28046032, 2017). "Proinflammatory cytokines Interleukin (IL)-6, IL-8 and TNF are increased and directly injury the lung endothelium, leading to cardiogenic and non-cardiogenic pulmonary edema." (PMID 37724533, 2023). "In this respect, it is of interest that the TNF-α inhibitor Etanercept diminished inflammation and coagulation in the lungs of ventilated mice without influencing alveolar-capillary permeability and pulmonary edema, which is in line with our present results." (PMID 21179479, 2010).
neuropathic pain (67 papers, 2011 to 2025). Chronic pain caused by damage to nerve fibers. "Several pro-inflammatory cytokines, including IL-1β, IL-6, IL-18, and TNF-α, have been implicated in the development of neuropathic pain." (PMID 35770074, 2022). "Formoterol as well as antidepressants counteracted the increase in TNFα associated with neuropathic pain and downregulated the activity of the glial NFκB-TNFα pathway, a key regulator of proinflammatory cytokine production." (PMID 32116538, 2019). "TNF-α, a neuropathic pain-related cytokine, caused thermal hyperalgesia and mechanical allodynia in rats." (PMID 25889774, 2015). "Different animal models of neuropathic pain had implicated the pivotal role of TNF-α in sensitization at both peripheral and central levels." (PMID 24278124, 2013). "In neuropathic pain models, IL-10 reduces macrophage infiltration and TNF-α levels at nerve injury sites, thereby effectively mitigating pain." (PMID 40165337, 2025). "In paclitaxel-induced neuropathic pain model, gallic acid has been reported to have ameliorative effect by moderating TNF-α and myeloperoxidase (MPO) levels." (PMID 40969950, 2025). "In summary, TNF-α-stimulated MSC-derived EV enhanced analgesic effects in neuropathic pain by directly modulating the excessive excitability of sensory neurons." (PMID 40755851, 2025). "EE can relieve neuropathic pain by reducing inflammatory mediators, such as proinflammatory cytokines (IL-1β, TNF-α, IL-6) and chemokines (CCL2, CCL3), among others, increasing anti-inflammatory substances (IL-10, Arg-1, CX3CL1) in the periphery and CNS." (PMID 40190342, 2025). "In neuropathic pain, the activation of Nrf2 reduces the levels of pro-inflammatory cytokines, such as tumor necrosis factor-alpha (TNF-α), and IL-1β, which are known to exacerbate pain signaling." (PMID 39204413, 2024). "During pathogenesis of neuropathic pain, activated microglia produce and release a variety of pro-inflammatory cytokines (e.g., IL-1β, TNFα, IL-6, and CCL2) and BDNF to sensitize spinal neurons." (PMID 33739978, 2021). "In the case of hesperidin, its antihyperalgesic effects in neuropathic pain have been related to the presence of cytokines concentrations (TNF-α, IL-1β and IL-6) in both peripheral and central tissues." (PMID 34371971, 2021). "It is known that IL-1β, IFN-γ, IL-17, IL-6 and TNFα are increased in nervous tissue in animal models of neuropathic pain, but also in cerebrospinal fluid and blood of patients with neuropathic pain." (PMID 32708184, 2020). "In a neuropathic pain model, microglia have been shown to release TNFα with effects on BDNF levels, which are known to modulate survival, although this is yet to be investigated in this context." (PMID 32742693, 2020). "Studies report the involvement of proinflammatory cytokines in pathological processes of pain, including TNF-α and IL-1β, which are found at high levels in animal models of neuropathic pain." (PMID 31049124, 2019). "In conclusion, GNF-2 significantly inhibits NF-κB activation and LPS-induced pro-inflammatory molecules including TNF-α and NO in microglia and in vivo models of chronic inflammatory and neuropathic pain." (PMID 31164822, 2019). "It has also been reported that ghrelin attenuates pain behaviors by decreasing TNF-α and IL-1β levels in the spinal cord and in a sciatic nerve injury model of neuropathic pain." (PMID 28182729, 2017). "Pro-inflammatory cytokines such as IL-1β, IL-6, and TNF-α have been associated with the behaviors of hyperalgesia and mechanical allodynia in the CCI model of neuropathic pain." (PMID 24605047, 2014). "In vivo, EGCG can inhibit the expressions of TLR4, NF-κB, HMGB1, TNF-α, and IL-1β, and promote the expression of IL-10 in neuropathic pain rats." (PMID 24692852, 2014). "Several studies have shown that the mRNA and protein levels of the pro-inflammatory cytokines TNF-α, IL-1β and IL-6 increased following chronic morphine injection and neuropathic pain." (PMID 24573601, 2014).
neuropathic pain (continued). "TNF-α also plays a pivotal role in the pathogenesis of peripheral neuropathic pain." (PMID 41394816, 2025). "Moreover, findings from neuropathic pain models—such as improvements in nerve conduction and reductions in pro-inflammatory cytokines (e.g., IL-6, TNF-α, CRP)—lend additional biological plausibility, although the certainty of this evidence remains limited." (PMID 41441449, 2025). "In experimental neuropathic pain models, repeated stimulation has been shown to downregulate pro-inflammatory cytokines (e.g., spinal IL-1β, hippocampal TNF-α), upregulate IL-10, and suppress microglial and astrocytic activation, thereby fostering adaptive plasticity and reducing hypersensitivity." (PMID 41245860, 2025). "Interestingly, it has been determined that the upregulation of IL-6, IL-1β, and TNF-α, among others, strongly influences neuropathic pain." (PMID 39684195, 2024). "TNF-α expression was increased in the early phase of a CCI-induced neuropathic pain model." (PMID 35204294, 2022). "C1q, proteases and TNFα are upregulated by microglia in neuropathic pain models and these are all known to mediate synaptic pruning, as reviewed above, and therefore the machinery necessary for either process is present in neuropathic pain." (PMID 32742693, 2020). "Thus, probably BET treatment is only effective on reducing pro-inflammatory mediators, such as TNF-α, CCL2, and CX3CR1, which are directly implicated in neuropathic pain." (PMID 31186006, 2019). "The intrathecal injection of exogenous TNF has been found to result in both mechanical and thermal hypersensitivity, while intrathecal injection of anti-TNF antibodies before peripheral nerve injury prevents the development of neuropathic pain in several neuropathic pain models." (PMID 31288837, 2019). "Moreover, Wnt, a downstream effecter of Kindlin-1, has been found to stimulate the release of pro-inflammatory cytokines, such as TNF-α and IL-18, in models of neuropathic pain." (PMID 28058534, 2017). "Thus, an immunotherapy that modulates the infiltration of immune cells, such as macrophages, and the upregulation of pro-inflammatory cytokines (e.g., IL-1β and TNF-α) would be a useful preventive treatment for neuropathic pain." (PMID 26797636, 2016). "Proinflammatory cytokines such as tumor necrosis factor-α (TNF-α) can influence long-term behavior in the CCI-induced neuropathic pain model, whereas interleukin-10 (IL-10) as an endogenous anti-inflammatory cytokine can downregulate the nerve's inflammatory reactions to the injury." (PMID 24605047, 2014). "Such elevated levels of TNF-α were previously observed with OXA-induced neuropathic pain." (PMID 23826152, 2013). "Similarly, high IL-6, IL-17A, and TNFα levels were observed in the serum of lumbar radiculopathy patient group compared with the neuropathic pain group, and Th17 was higher in the venous blood of lumbar radiculopathy patients group compared with the neuropathic pain group." (PMID 35309927, 2022). "It is known that TNF-α induces the expression of certain MMPs, including gelatinase, and these proteins control TNF-α expression in several diseases and in neuropathic pain." (PMID 40362812, 2025). "In this study, we demonstrated that miR-101b-3p, which was enriched in EV derived from TNF-α-primed MSC, effectively attenuated the upregulation of Nav1.6 expression in a neuropathic pain model." (PMID 40755851, 2025). "In our study, PTP1B‐IN‐1 administration effectively suppressed the elevated Iba‐1, GFAP, TNF‐α, IL‐6, and IL‐1β in SNI‐induced neuropathic pain rats." (PMID 38334011, 2024). "Studies have shown that NF-κB is observed to regulate the expression of pro-inflammatory cytokines such as TNF-α, IL-1β and IL-6 in DRG and spinal cord in neuropathic pain." (PMID 33095154, 2020). "Morin reduced several inflammatory biomarkers (PARP, iNOS, COX-2, NF-κB and phospho-NF-κB, TNF-α and IL-6) in CCI-induced neuropathic pain model." (PMID 32150953, 2020).